NLRP3 (NLR family pyrin domain containing 3)
Diseases named in the same sentence as NLRP3 in open-access papers (continued):
Sharing a sentence is not in itself a finding about the gene and the disease.
rickettsioses (1 paper, 2025). "Our results highlight that R. conorii-induced NLRP3-associated reduction and disruption of ZO-1 likely lead to interrupted endothelial junction integrity that is the fundamental pathophysiological effect of severe rickettsioses." (PMID 39679710, 2025). "Although NLRP3 contributes to the activation of ASC inflammasome by R. australis in macrophages, NLRP3 plays a negligible role in host protection in vivo, suggesting that NLRP3 is possibly involved in mediating pathogenesis of rickettsioses." (PMID 39679710, 2025). "These new findings may lead to a promising therapeutic strategy for severe rickettsioses by targeting NLRP3 to ameliorate endothelial permeability/inflammation/injury as an adjunctive approach to accompany anti-rickettsial treatment." (PMID 39679710, 2025). "Therefore, our findings suggest that R. conorii reduces microvascular junction integrity by activating NLRP3/ZO-1 signal cascades to promote the extravasation of plasma and leukocytes from blood vessels into tissues in severe rickettsioses." (PMID 39679710, 2025). "The experimental models of rickettsioses further elucidated that ASC, but not NLRP3 inflammasome, is essential for the host protective immune response against R. australis." (PMID 39679710, 2025).
sacroiliitis (1 paper, 2025). "We also present a unique case of NLRP-3 AID with sacroiliitis as a prominent feature." (PMID 40757135, 2025). "Our cases seek to highlight the myriad manifestations and severity of NLRP3-AID in the Indian population, and we report a novel presentation of this disease in P3 in the form of Grade 4 sacroiliitis." (PMID 40757135, 2025).
sarcoma (1 paper, 2021). A usually aggressive malignant neoplasm of the soft tissue or bone. "3′methylcholanthrene (MCA)-induced sarcomas in mice deficient in NLRP3 had decreased tumor burden compared to wild-type mice, attributed to NLRP3-mediated suppression of NK cell immune surveillance." (PMID 33572196, 2021).
scoliosis (1 paper, 2025). A congenital or acquired spinal deformity characterized by lateral curvature of the spine. "Notably, knockdown of NOD-like receptor family pyrin domain containing 3 (NLRP3) has been shown to protect against PMD and scoliosis by remarkably inhibiting pyroptosis, apoptosis, and IL-1β expression in paravertebral muscle cells." (PMID 40722201, 2025).
sensitization (1 paper, 2025). "Our results demonstrate that NLRP3 plays a critical role for the integrity of the epithelial barrier protecting against allergen uptake and possibly allergic sensitization." (PMID 41394833, 2025).
Skin detachment (1 paper, 2024). Loss of sections of skin either spontaneously or after gentle handling. "The NLRP3 Inflammasome plays a crucial role in the pathogenesis of Stevens Johnson Syndrome/Toxic Epidermal Necrolysis and may correlate with the degree of severity of skin detachment and ocular surface disease." (PMID 39026932, 2024).
skin sensitization (1 paper, 2025). An immunological response to previous exposure to a substance which results in an inflammatory skin reaction. "Utilizing our established immune-competent skin model, we evaluated the effects of PsA-D on NiSO4-induced activation by analyzing mRNA levels of CD54, CD86, IL-8, IL-6, IL-1β, NLRP3, and COX-2, thereby exploring its potential as a novel therapy for skin sensitization and allergic skin inflammation." (PMID 40559654, 2025).
skin ulceration (1 paper, 2025). "Both NK and CD8+ T cells have been shown to kill Leishmania protozoa-infected cells, leading to the release of DAMPs, activation of NLRP3 inflammasomes, and IL-1β, which exacerbate skin ulceration." (PMID 39319843, 2025).
Spinal instability (1 paper, 2023). "In addition, immunohistochemical staining showed the levels of p-PI3K, p-p65, and NLRP3 of the MA group were similar to control but lower than spinal instability group." (PMID 36401729, 2023).
spondyloarthritis (1 paper, 2025). "Cytokine-mediated inflammation involving IL-1/NLRP3, TNF-α, IL-6, and IL-17 pathways has been implicated in both spondyloarthritis and pericardial disease." (PMID 41357030, 2025).
sporotrichosis (1 paper, 2021). The commonest and least serious of the deep mycoses, characterized by nodular lesions of the cutaneous and subcutaneous tissues. "NLRP3 and caspase-1 knockout mice were more susceptible to sporotrichosis." (PMID 34908455, 2021). "The proportions of Th17 cells and Th1/Th17 cells in gene knockout mice infected with sporotrichosis were decreased, suggesting that the NLRP3 inflammasome has antisporotrichosis immune activity." (PMID 34908455, 2021). "Indeed, the regulatory effects of the NLRP3/caspase-1 pyroptosis pathway against sporotrichosis upon Nd:YAG 1,064-nm laser treatment are worthy of further study." (PMID 34908455, 2021).
Staphylococcus pneumonia (1 paper, 2015). "It has been reported that bacterial hemolysins, for example, listeriolysin O of Listeria monocytogenes, hemolytic cytolysin pneumolysin of Staphylococcus pneumonia and hemolysin of S. aureus, can induce the release of IL-1β through activation of NLRP3 inflammasome." (PMID 26052324, 2015).
Stevens-Johnson syndrome (1 paper, 2024). Stevens-Johnson syndrome is a limited form of toxic epidermal necrolysis characterized by destruction and detachment of the skin epithelium and mucous membranes involving less than 10% of the body surface area. "This study is focused on determining the role of NLRP3 Inflammasome in the pathogenesis of Stevens Johnson Syndrome/Toxic Epidermal Necrolysis." (PMID 39026932, 2024). "The identification of the roles of NLRP3 in Stevens Johnson Syndrome/Toxic Epidermal Necrolysis would bridge the gaps in the basic understanding regarding the pathogenesis of this disease spectrum." (PMID 39026932, 2024).
Stillbirth (1 paper, 2025). Death of the fetus in utero after at least 22 weeks of gestation. "Although limited research has been conducted regarding a potential role of the NLRP3 inflammasome in the pathology of FGR and stillbirth, other placental pathologies with a similar inflammatory profile have suggested a role for the NLRP3 complex." (PMID 40260875, 2025).
substance abuse (1 paper, 2024). The use of a drug for a reason other than which it was intended or in a manner or in quantities other than directed. "Moreover, activation of TLRs (toll-like receptors) by HIV, gut microbes, and substance abuse further activates the NLRP3 inflammasome pathway." (PMID 38781301, 2024).
sunburn (1 paper, 2024). An inflammatory reaction from ultraviolet radiation characterized by transient redness, tenderness and occasional blistering. "Sunburn is a cutaneous sterile inflammation instigated by UVB-induced NLRP3 inflammasomes in keratinocytes, and we have shown that UVB-induced nuclear DNA damage triggers NLRP3 inflammasome activation in keratinocytes." (PMID 38499149, 2024).
testicular diseases (1 paper, 2024). "Recent researches have shown higher expression of NLRP3 in a number of testicular diseases." (PMID 38468237, 2024).
Testicular regression syndrome (1 paper, 2024). Testicular regression syndrome (TRS) is a developmental anomaly characterized by the absence of one or both testicles with partial or complete absence of testicular tissue. "In our experiment, NLRP3 showed weak expression in cryptorchid tissues, which is considered to be related to the fact that the cryptorchid tissues selected were testicular tissues of testicular regression syndrome, rather than true cryptorchid tissues." (PMID 39840312, 2024).
Thiamine deficiency (1 paper, 2025). Thiamine deficiency is a condition that occurs due to not enough thiamine (vitamin B1). "Additionally, thiamine deficiency appears to be implicated in the upregulation of TLR4 and NLRP3 pathways, further perpetuating cellular energy deficits and oxidative stress." (PMID 40700076, 2025).
thromboangiitis obliterans (1 paper, 2018). A rare inflammatory non-necrotizing vascular disease affecting the small- and medium-sized arteries and veins of the upper and lower extremities characterized by endarteritis and vaso-occlusion due to occlusive thrombus development. "LA suppressed NLRP3 gene expression by blocking the Syk--p38/JNK pathway and reduced damage to the rats' limbs in the thromboangiitis obliterans model." (PMID 30158835, 2018).
thymic atrophy (1 paper, 2021). "The Dixit group first demonstrated the role of the NLRP3 inflammasome in promoting age-related thymic atrophy and immune senescence." (PMID 33435298, 2021). "The researchers found that deletion of the inflammasome components NLRP3 and ASC significantly increased the number of cortical thymic epithelial cells and T cell progenitors, which reduced aging-related thymic atrophy." (PMID 33435298, 2021).
tongue cancer (1 paper, 2017). A malignant neoplasm affecting the tongue. "Nlrp3−/− and Caspase1−/− mice showed later occurrence of tongue carcinoma and smaller tumor area than wild-type mice." (PMID 28637493, 2017).
tongue tumor (1 paper, 2023). "In conclusion, the obtained data demonstrated that BAY-117082 at doses of 2.5 mg/kg and 5 mg/kg were able to reduce the tongue tumor area as well as the degree of metastasis in lymph node, lung, and spleen tissues through the NLRP3 inflammasome pathway inhibition." (PMID 37345134, 2023).
Trichinella spiralis infection (1 paper, 2020). "The NLRP3 have been shown to contribute to immune responses to infection with Trypanosoma cruzi, Toxoplasma gondii, Paracoccidioides brasiliensis, and Leishmania species, whereas the role of NLRP3 in the immune response to Trichinella spiralis infection is not yet clear." (PMID 32854770, 2020).
Truncal dystonia (1 paper, 2019). Truncal dystonia is a form of focal dystonia (see this term), characterized by involuntary back arching often associated with pain and severe motor disability. "In accord with these observations, MPTP intoxication caused a severe truncal dystonia in WT mice, but the observed effects were reduced in Nlrp3-deficient mice." (PMID 29786072, 2019).
uveal melanoma (1 paper, 2023). A melanoma derived from melanocytes of the uveal tract. "Here, we show that NLRP3 and IL‐1β levels in uveal melanoma are minimal." (PMID 36707938, 2023).
Varicose veins (1 paper, 2019). Enlarged and tortuous veins. "As for varicose veins, NLRP3 inflammasome has a downward tendency, which suggested that NLRP3 inflammasome mediated inflammation may not contribute to the pathogenesis of varicose veins." (PMID 30941060, 2019).
venous thromboembolism (1 paper, 2025). Occlusion of the lumen of a vein by a thrombus that has migrated from a distal site via the blood stream. "In recent years, research has increasingly focused on the role of the NLRP3 inflammasome in venous thromboembolism (VTE)." (PMID 40520933, 2025).
vitamin D deficiency (1 paper, 2021). A nutritional condition produced by a deficiency of VITAMIN D in the diet, insufficient production of vitamin D in the skin, inadequate absorption of vitamin D from the diet, or abnormal conversion of vitamin D to its bioactive metabolites. "In conclusion, our current study confirmed NLRP3 inflammasome pathway activation and serum/vitreous vitamin D deficiency in PDR patients." (PMID 34722576, 2021). "Our current findings imply that vitamin D deficiency may be a possible mechanism to activate NLRP3 inflammasome pathway during PDR pathogenesis." (PMID 34722576, 2021).
xerostomia (1 paper, 2026). Dryness of the mouth resulting from reduced salivary secretion. "The focus score and severity of xerostomia strongly correlate with elevated NLRP3 and caspase-1 expression levels in the labial salivary glands of patients with SS." (PMID 41596738, 2026).
infection (1,094 papers, 2009 to 2026). The state of being infected such as from the introduction of a foreign agent such as serum, vaccine, antigenic substance or organism. "In this review, we summarize recent advances that have expanded our understanding of the diverse classes of NLRP3 stimuli and highlight breakthroughs in elucidating the molecular mechanisms underlying both infection-driven and sterile inflammation." (PMID 42162153, 2026). "While our prior work established PmCQ2-driven NOD-like receptor thermal protein domain associated protein 3 (NLRP3) inflammasome activation, the role of pyroptosis in pulmonary pathology during infection remains unresolved." (PMID 41693732, 2026). "The NLRP3 inflammasome is essential to the innate immune system, which provides defense against infections caused by bacteria, fungi, and viruses." (PMID 41261343, 2025). "NLRP3 is an intracellular receptor protein of the inflammasome family that acts as a sensor for the loss of cellular homeostasis during infections and sterile injury." (PMID 40053580, 2025). "After infection with influenza A, mice deficient in NLRP3 had decreased survival and inflammatory cytokine production, suggesting an immune response dependent on NLRP3 activation." (PMID 39878363, 2025). "It is interesting that the pulmonary IL-6 level, but not the IL-1β or TNFα levels, significantly decreased in mice deficient in caspase-11 or NLRP3 upon infection." (PMID 40034692, 2025). "Knockdown of Nlrp3 by CRISPR-Cas9 (edition efficiency of about 75%) resulted in higher susceptibility to ST infection, suggesting that Nlrp3 is crucial for host survival and bacterial clearance." (PMID 41360763, 2025). "We further examined ASC oligomerization, an indicator of inflammasome activation, in BMDMs deficient in caspase-1, caspase-11, or NLRP3 upon infection with K. pneumoniae." (PMID 40034692, 2025). "Regarding immune cell dynamics, we observed the same pattern as with Nlrp3 deficiency: increased neutrophil recruitment and total numbers under both homeostasis and infection, with selective neutrophil elimination by ST in a Gsdme-dependent manner." (PMID 41360763, 2025). "Controlled activation of the NLRP3 inflammasome is required for host protective responses during pathogenic infections." (PMID 40307577, 2025). "It seems, therefore, that multiple factors, such as the parasite species and susceptibility of the host to infection, influence NLRP3 activation and lead to its dual action during Leishmania infection." (PMID 38623843, 2024). "ASC and NLRP3 play an important role in inflammasome complex activation caused by infectious pathogens and in infection-induced macrophage activation." (PMID 38339007, 2024). "The therapeutic potential of targeting caspase-1 has been largely explored; however, this strategy would also alter responses downstream of NLRP3 and result in increased susceptibility to infections." (PMID 39459869, 2024). "Since NLRP3 inhibitors suppress parts of the immune response, there is a theoretical risk of increased susceptibility to infections." (PMID 39188718, 2024). "Risk signals such as infection, tissue damage and metabolic disorders can activate the innate immune signaling receptor NLRP3 in cells." (PMID 38698431, 2024). "They found that in case-control analysis, IL-1β rs1143643 is linked with HPV protection, while NLRP3 rs10754558 has been linked with a lower risk of infection with HPV." (PMID 39769450, 2024). "In the current study, we treated BC 5,637 cells with LPS to mimic the inflammatory microenvironment caused by infection and found that LPS notably increased the levels of NLRP3 and inflammatory cytokines, including IL-1β, IL-18, and TNF-α." (PMID 39144184, 2024). "Gsdmd–/– macrophages and mice exhibit less NLRP3 inflammasome activation and are highly susceptible to infection by several Leishmania species, confirming the role of GSDMD for inflammasome-mediated host resistance." (PMID 36828815, 2023).
infection (continued). "Elegant studies with an NLRP3 inhibitor showed that NLRP3 signalling drives disease later in infection, likely by amplifying pathogenic inflammation." (PMID 36695550, 2023). "Blocking NLRP3 with MCC950 24 h post-infection resulted in accelerated weight loss and increased mortality in mice." (PMID 37508374, 2023). "On the one hand, if NLRP3 inflammasome activation is blocked, the immune response against pathogenic microorganisms cannot be effectively induced, resulting in severe infections." (PMID 37243164, 2023). "NLRP3 (NLR family, pyrin domain containing 3) inflammasome complex is an intracellular multiprotein complex responsible for several innate immune processes associated with infection, inflammation, and autoimmunity." (PMID 36859349, 2023). "CFT073 infection of NLRP3-deficient cells significantly upregulated 3228 gene entities and downregulated 1398 gene entities compared to unstimulated NLRP3-deficient cells." (PMID 37759520, 2023). "NLRP3 inflammasome-mediated pyroptosis is a form of programmed cell death implicated in the clearance of pathogenic infections." (PMID 37511451, 2023). "The infection of cells by EV71 can activate the NLRP3 inflammasome, which then causes the creation and release of proinflammatory cytokines including active IL-1β." (PMID 38249297, 2023). "Using MCC950 (NLRP3 inhibitor), they observed decreased inflammation, abrogated osteoclastogenic bone loss, and myositis associated with infection." (PMID 36298668, 2022). "In contrast, Staphylococcus aureus toxin-induced infection is associated with exacerbated inflammation due to NLRP3 engagement downstream of MLKL activation." (PMID 36127465, 2022). "Among the numerous NLRPs encoded, the NLRP3 inflammasome is the best described and is relevant in the context of infection by L. interrogans." (PMID 35937697, 2022). "Like in GBS infection, NLRP3 activation was protective, reducing animal’s susceptibility to infection with S. aureus." (PMID 35369454, 2022). "Cytokines inhibitors remain limited due to infection risk, whereas NLRP3 inflammasome inhibitors show the best anti-inflammatory effects in animal models." (PMID 35833125, 2022). "Using a mouse model of infection, the authors have demonstrated that activation of NLRP3 by N protein has been associated with lung injury and a cytokine storm, the two hallmarks of Covid-19 infection." (PMID 35663964, 2022). "The NLRP3 inflammasome, an innate immune response protein complex, can be activated upon cellular infection or stress induced by PAMP, the so call pathogen-associated molecular patterns or DAMP, damage-associated molecular patterns." (PMID 34983566, 2022). "In one, cytotoxic activities involving CD8+ T and NK cells linked to inflammatory executors such as NLRP3 inflammasome, IL-1β, and neutrophils mediate exacerbated tissue damage in response to L(V)b infection." (PMID 35770175, 2022). "In previous work, researchers have demonstrated that MFN2 can interaction with NLRP3 to promote the NLRP3 inflammasome activation and IL-1β secretion in response to the infection of RNA virus or pathogenic bacteria." (PMID 36588561, 2022). "Using a mouse model, they showed that NLRP3 infection was associated with high levels of inflammatory symptoms." (PMID 36298668, 2022). "The assembly of the NLRP3 inflammasome requires a further activation signal, referred to as signal 2, which is usually provided by the bacterial toxin nigericin or other infection or stress-associated molecules." (PMID 33430226, 2021). "The NLRP3 inflammasome is activated during various infections, and animals with NLRP3 deficiency have a high mortality rate upon infection." (PMID 33430226, 2021). "For Fn U112 infection, cysteine mutations had little impact on NLRP3-dependent IL-1β maturation or the frequency of ASC speck-containing cells." (PMID 34745125, 2021). "NLRP3 is activated in response to various noxious stimuli or damage signals associated with pathogen infection." (PMID 33410748, 2021).